GATA4 (GATA binding protein 4)
Diseases named in the same sentence as GATA4 in open-access papers (continued):
Sharing a sentence is not in itself a finding about the gene and the disease.
osteoarthritis (3 papers, 2018 to 2025). A noninflammatory degenerative joint disease occurring chiefly in older persons, characterized by degeneration of the articular cartilage, hypertrophy of bone at the margins and changes in the synovial membrane. "Our work demonstrates that the aging-associated increase of GATA4 in chondrocytes plays a vital role in OA progression, which may also serve as a target to reduce osteoarthritis in the older population." (PMID 40166328, 2025). "Key molecules such as GATA4 and sirtuins could represent potential therapeutic targets in the treatment of osteoarthritis, underlining the importance of thoroughly investigating the underlying biological mechanisms." (PMID 39335461, 2024). "Overall, autophagy prevents cellular senescence by suppressing GATA4, making it a potential therapeutic target for osteoarthritis." (PMID 39335461, 2024). "RT-qPCR and western blotting analysis was performed to determine the expression of GATA4 in synoviocytes from osteoarthritis (OA) and RA patients." (PMID 29717129, 2018).
ovarian tumor (3 papers, 2013 to 2023). "Moreover, some studies reported that methylation in the GATA4 and GATA6 promoter region could play an important role in ovarian carcinogenesis, elevated GATA4 and lower GATA6 mRNA levels are associated with better prognosis in ovarian tumours." (PMID 35488350, 2022). "We compared the bulk transcriptomes of hiPSCs, COV434 and KGN ovarian tumor cells, and sorted FOXL2+CD82+ granulosa-like cells from day 5 of a polyclonal differentiation with expression of our previously identified top TFs (NR5A1, TCF21, GATA4, and RUNX1)." (PMID 36803359, 2023).
polycystic ovary syndrome (3 papers, 2024 to 2025). A disorder that manifests as multiple cysts on the ovaries. "In mice, the conditional knockout of GATA4 in hypothalamic neurons and glia leads to reproductive abnormalities, mimicking conditions such as polycystic ovary syndrome (PCOS)." (PMID 41200545, 2025). "The GATA4/NEIL2 locus also has previous links with ovulatory dysfunction and polycystic ovary morphology." (PMID 38408933, 2024). "In polycystic ovary syndrome (PCOS), AMH levels are significantly higher due to an increased number of granulosa cells (GCs) and enhanced transcriptional activity mediated by Foxl2, Sox9, and Gata4." (PMID 40724853, 2025).
teratocarcinoma (3 papers, 2010 to 2023). A germ cell tumor characterized by the presence of an embryonal carcinoma component and a teratoma component. "However, the expression levels of the pluripotency markers Oct4 and Nanog and lineage-specific gene markers Mvh, Gata4, Pax6 and Bry significantly differ between pluripotent stem and teratocarcinoma cells." (PMID 31143371, 2019). "Although, it is unknown how RA signals stimulate GATA4/6 expression in this system, previous studies of pluripotent F9 teratocarcinoma cells have identified GATA4 and GATA6 as transcriptional targets of RARγ and RARβ2 signaling complexes, respectively." (PMID 20644631, 2010). "To support the results obtained in ESC cardiac differentiation, we used teratocarcinoma-derived P19 cells, and, to verify the proper differentiation of P19 cells into cardiomyocytes, we evaluated the gene expression of key markers of cardiac differentiation: Nkx 2.5, Gata-4, Apj, and Mlc-2." (PMID 37569627, 2023).
viral infection (3 papers, 2012 to 2025). "Genetic lesions and environmental insults such as interstitial deletion of 8p32.1 to GATA4 gene, chemicals, viral infection, or nutritional deficiency would perturb the cardiac morphogenesis and result in axial extension defects." (PMID 22857009, 2012). "The effectiveness of virus infection was evaluated by qPCR of GATA4 in NP tissue." (PMID 39572532, 2024). "Overexpression of JAK1, TYK2, MAP2K1, IFNG, TRPM2, and ADCY9 significantly inhibited viral infection, whereas overexpression of SNX27, GATA4, EHMT2, PCBP2, SMARCA4, and SLX4 enhanced viral infection." (PMID 40530850, 2025).
adrenal cortical carcinoma (2 papers, 2013 to 2022). "Expression of master-regulator SF1 and the key adrenal transcription factors GATA4 and GATA6 in the HAA1 line was present, but lower than that in the control NCI-H295R human adrenal cortical carcinoma cell line." (PMID 36614027, 2022).
Bicuspid aortic valve (2 papers, 2012 to 2022). The presence of an aortic valve with two instead of the normal three cusps (flaps). "Recently, disease modeling of GATA4 and TBX5 pathogenic variants in human iPSC-derived CM and iPSCs-derived EC from patients with bicuspid aortic valve and calcific aortic valve disease with NOTCH1 haploinsufficiency have predicted that CHD-linked GRN is sensitive to gene dosage." (PMID 35970860, 2022).
Cardiac Arrhythmias (2 papers, 2018 to 2019). Any disturbances of the normal rhythmic beating of the heart or MYOCARDIAL CONTRACTION. "A methylated GATA4 gene was also associated with a greater chance of airflow obstruction, defined by the Global Initiative for Chronic Obstructive Lung Disease (GOLD) criteria as FEV1/FVC less than 70%." (PMID 31703266, 2019).
colorectal tumors (2 papers, 2014 to 2021). "Methylation of the SFRP2, GATA4/5, NDRG4 and VIM promoters in fecal DNA is associated with the presence of colorectal tumors." (PMID 25202404, 2014).
Disorder of Sex Development (2 papers, 2015 to 2018). "The critical role of GATA4 in human gonadal development is highlighted by a familial case of 46, XY DSD (Disorder of Sex Development) associated with a heterozygous GATA4 p.Gly221Arg mutation." (PMID 26473289, 2015).
endometriosis (2 papers, 2017 to 2025). The growth of functional endometrial tissue in anatomic sites outside the uterine body. "In the ovary, (a tissue commonly affected by endometriosis) the prominent involvement of MFHAS1, CLDN23, USP4, and GATA4 was identified, all of which are regulated by eQTLs." (PMID 40863222, 2025). "From the Cancer Hallmarks perspective, GATA4, C2, MICB, and CLDN23 were implicated in evading immune destruction and tissue invasion, suggesting that even within intestinal tissues, relevant molecular signals associated with the pathophysiology of endometriosis may be present." (PMID 40863222, 2025).
Holt-Oram syndrome (2 papers, 2024 to 2025). Holt-Oram syndrome (HOS) is the most common form of heart-hand syndrome and is characterized by skeletal abnormalities of the upper limbs and mild-to-severe congenital cardiac defects. "TAPVD has been found in conjunction with several genetic syndromes, including mutations in GATA4 and ZIC3, as well as cardiofaciocutaneous syndrome, Holt-Oram syndrome, Williams syndrome, and cat-eye syndrome, suggesting a possible genetic predisposition." (PMID 40780769, 2025). "Holt-Oram syndrome is partially caused by variants in the TBX5 gene, and GWAS studies on AF have shown several significant loci with nearest genes known to be important for heart development and causal for CHD, such as NKX2-5, GATA4, GJA1, and GJA5." (PMID 38454350, 2024).
hyperlipidemia (2 papers, 2022). "We showed transcription factor GATA4 preferentially binds the T allele of rs651821, the protective allele for hyperlipidemia, which promoted APOA5 expression in liver cells and individuals with the TT genotype of rs651821." (PMID 35046404, 2022). "Collectively, this suggests a therapeutic model for the synergistic effect of APOA5 and GATA4 on TG level, which may help control an individual’s susceptibility to hyperlipidemia and other metabolic abnormalities." (PMID 35046404, 2022). "Cluster 1 represents a distinct population of cells expressing genes involved in inflammation (Ifi27l2a), hyperlipidemia (Gata4), VSMC phenotypic modulation (Meox1), calcification and bone formation (Htra4, Meox1)." (PMID 35163719, 2022). "We suggest elevating GATA4 activity could provide a therapeutic potential for treating the development of hyperlipidemia." (PMID 35046404, 2022).
hypertrophic cardiomyopathy (2 papers, 2016 to 2019). A condition in which the myocardium is hypertrophied without an obvious cause. "We isolated cardiac tissues from ISO-treated 8-week-old mice, and results showed that GATA4 level was significantly enhanced in ISO-treated cKO mice, suggesting that activation of GATA4 mediates the hypertrophic cardiomyopathy in Kindlin-2 cKO mice." (PMID 31767831, 2019).
hypothyroidism (2 papers, 2015 to 2024). Abnormally low levels of thyroid hormone. "Consistently, it was reported that hypothyroidism induces D2 mRNA in rodent heart, where both TRs and GATA4 are expressed." (PMID 26571013, 2015).
inflammatory bowel disease (2 papers, 2012 to 2013). A spectrum of small and large bowel inflammatory diseases of unknown etiology. "It will be interesting to evaluate the possible role of GATA-4 in the increased expression of claudin-2 in different human epithelial pathologies, including inflammatory bowel disease and cancer." (PMID 23409073, 2013). "The transcription factor GATA4, which is involved in TGF-β signaling and is upregulated in patients with inflammatory bowel disease, was also downregulated." (PMID 23300544, 2012).
Leydig cell tumor (2 papers, 2012 to 2022). A sex cord-stromal tumor occurring in the testis and rarely in the ovary. "Interestingly, GATA4 expression is significantly higher in both Sertoli and Leydig cell tumors, suggesting that GATA4 might influence cell proliferation during tumorigenesis in human testicular somatic cells." (PMID 35692407, 2022).
mastitis (2 papers, 2024). Inflammation of breast tissue during lactation or postpartum due to an obstructed duct or infection. "The network analysis showed that the CSF1R, RHO, RCVRN, CAV3, and GATA4 genes were core nodes, suggesting that these genes could serve as candidate molecular markers for mastitis." (PMID 38674399, 2024). "Notably, the lncRNA-miRNA-mRNA ternary co-expression network of RHO, RCVRN, CSF1R, CAV3, and GATA4 genes is likely to be involved in the regulation of mastitis in Xinjiang brown cattle." (PMID 38674399, 2024).
neonatal diabetes mellitus (2 papers, 2024). Neonatal diabetes mellitus presents as hyperglycemia, failure to thrive and, in some cases, dehydration and ketoacidosis which may be severe with coma, in a child within the first months of life. "Mutations in GATA6 are associated with human pancreas agenesis, and mutations in GATA4, and MNX1 cause permanent neonatal diabetes mellitus." (PMID 39322760, 2024). "The case report shows the safety and efficacy of insulin treatment with Advanced Hybrid Closed Loop (AHCL) system in a young patient affected by permanent neonatal diabetes mellitus (PNDM) due to chromosome 8 deletion syndrome involving the GATA4 gene." (PMID 39457190, 2024).
osteosarcoma (2 papers, 2018 to 2025). A usually aggressive malignant bone-forming mesenchymal neoplasm, predominantly affecting adolescents and young adults. "Likewise, SOX9 expression was shown to drive mesenchymal proliferation and extracellular matrix remodeling in chordoma and osteosarcoma models, while GATA4 has recently been linked to myogenic reprogramming and mesodermal lineage persistence." (PMID 41303462, 2025).
sarcoma (2 papers, 2025). A usually aggressive malignant neoplasm of the soft tissue or bone. "GATA4, although less studied in sarcomas, participates in mesodermal and myogenic transcriptional networks, regulating cellular plasticity and stress responses, interacting with GATA4 during mesenchymal tissue remodeling." (PMID 41303462, 2025).
serous ovarian adenocarcinoma (2 papers, 2009 to 2019). "Statistically significant higher methylation leading to the loss of GATA4 expression in endometrioid type compared to serous ovarian adenocarcinoma has been reported." (PMID 31744494, 2019). "GATA4 expression is absent in the majority of serous ovarian cancer, and GATA6 is also absent in many but also positive in some cases." (PMID 19649254, 2009).
serous ovarian carcinoma (2 papers, 2013 to 2023). "The GATA4 gene is believed to dictate distinct pathological pathways leading to serous ovarian carcinomas." (PMID 24565108, 2013). "In addition, the same group recently investigated PCDH17 gene methylation (with other genes namely CDH13, HNF1B and GATA4) in high grade serous ovarian carcinoma." (PMID 36698136, 2023).
soft tissue sarcoma (2 papers, 2022 to 2025). A malignant neoplasm arising from muscle tissue, adipose tissue, blood vessels, fibrous tissue, or other supportive tissues excluding the bones. "Similarly, results obtained using downregulated DEGs include transcription factors previously associated with poor prognosis for human soft tissue sarcomas (GATA4, GATA3)." (PMID 36099287, 2022). "In agreement with previous reports, our data expand on earlier evidence of SOX9, GATA3, and GATA4 dysregulation in soft tissue sarcomas." (PMID 41303462, 2025).
squamous cell carcinoma (2 papers, 2017 to 2023). A carcinoma arising from squamous epithelial cells. "Squamous cell carcinomas showed frequent genic amplification of CCND1 and SOX2 and/or TP63, while ERBB2, VEGFA, GATA4, and GATA6 were more commonly amplified in adenocarcinomas." (PMID 37893095, 2023). "Squamous cell carcinomas showed frequent genomic amplifications of CCND1 and SOX2 and/or TP63, whereas ERBB2, VEGFA and GATA4 and GATA6 were more commonly amplified in adenocarcinomas." (PMID 28052061, 2017).
teratoma (2 papers, 2019 to 2021). A non-seminomatous germ cell tumor characterized by the presence of various tissues which correspond to the different germinal layers (endoderm, mesoderm, and ectoderm). "Although the mechanism of teratoma formation is unknown, global knockdown of the Gata4 gene by siRNA also induced the formation of OTs41." (PMID 33568756, 2021). "An analysis of teratoma tissue showed the expression of GATA4, BRACHYURY, and TUJ1 proteins, indicating that teratoma tissue had cells representing the endoderm, mesoderm, and ectoderm, respectively." (PMID 31888235, 2019).
Testicular atrophy (2 papers, 2019 to 2024). Wasting (atrophy) of the testicle (the male gonad) manifested by a decrease in size and potentially by a loss of fertility. "Deletion of Gata4 in Leydig cells and Sertoli cells causes testicular atrophy and defects in the motility and quantity of sperm." (PMID 38724675, 2024). "GATA4-deficient mice showed age-dependent loss of fertility as testicular atrophy and decrease of sperm motility." (PMID 31569653, 2019).
Turner syndrome (2 papers, 2022 to 2024). Turner syndrome is a chromosomal disorder associated with the complete or partial absence of an X chromosome. "When attempting to replicate the differentiation process of embryonic granulosa cells, we observed the downregulation of specific genes—GATA4, FOXL2, AMHR2, CYP19A1, and FSH—in Turner syndrome-derived granulosa cells (TS-GCs)." (PMID 39543104, 2024). "The pathogenic variants reported comprised one case of mosaic Turner syndrome (45,X) not detected on CMA, and four variants in the genes ARMC4, ANKRD11, GATA4 and NSD1, all of which would have been amenable to detection by whole exome sequencing in the PAGE and CUIMC studies." (PMID 34411415, 2022).
acute myeloid leukemia (1 paper, 2015). Acute myeloid leukemia (AML) is a group of neoplasms arising from precursor cells committed to the myeloid cell-line differentiation. "The prognostic significance of GATA4 expression and promoter methylation was assessed in 105 cases of Chinese pediatric acute myeloid leukemia patients with clinical follow-up records." (PMID 26490736, 2015). "Currently, the expression of GATA4 and the methylation status of its promoter in pediatric acute myeloid leukemia have not been reported." (PMID 26490736, 2015).
alcohol use disorder (1 paper, 2025). "One of the top ten downregulated genes with alcohol preference included Gata4 which has been linked to alcohol use disorder (AUD) previously at the gene level." (PMID 41153338, 2025).
Alzheimer disease (1 paper, 2018). A progressive, neurodegenerative disease characterized by loss of function and death of nerve cells in several areas of the brain leading to loss of cognitive function such as memory and language. "Interestingly, among the deregulated proteins associated to Alzheimer’s disease, we found previously reported AD-associated proteins, including the accumulation of GATA4 and Chromogranin-A, or MBL2, whose over-expression has been described in the surrounding of blood vessels in AD brain patients." (PMID 29541381, 2018).
aneurysm (1 paper, 2024). Bulging or ballooning in an area of an artery secondary to arterial wall weakening. "In other cellular contexts, Gata4 has been shown to promote induction of the pro-inflammatory senescence-associated secretory phenotype (SASP) as well as transcription of the lncRNA Malat1, which promotes aneurysm development in other mouse models." (PMID 38883722, 2024).
aortic coarctation (1 paper, 2019). "According to GATA4 genotypes, a 5‐prime UTR variant rs368418329, GT (42% of the cases) and GG (46% of the cases) genotypes showed the most frequent presentation in cases (24 ASD, 48 VSD, six PDA, six aortic coarctation and 12 Fallot)." (PMID 30834692, 2019).
Arthritis (1 paper, 2018). Inflammation of a joint. "Reduced severity of arthritis in sh GATA4-treated mice was associated with decreased infiltration of immune cells in affected joints." (PMID 29717129, 2018). "To investigate the expression of GATA4 in synovium tissue, we conducted adjuvant-induced arthritis (AIA) rat model, one of the patterns that are characterized by the formation of pannus." (PMID 29717129, 2018). "However, CIA mice treated with sh GATA4 developed less severity and lower incidence of arthritis as determined by clinical scores." (PMID 29717129, 2018).
atrophic gastritis (1 paper, 2008). "GATA-4 and GATA-6 are also expressed in hyperplastic neuroendocrine cells associated with atrophic gastritis." (PMID 18405344, 2008).
autoimmune disease (1 paper, 2021). A disorder resulting from loss of function or tissue destruction of an organ or multiple organs, arising from humoral or cellular immune responses of the individual to their own tissue constituents. "SPIB, as well as E2F2, GATA4 and TCF7L2 have been associated with other autoimmune diseases through differential gene expression and genetic polymorphisms, respectively." (PMID 33915751, 2021).
B-cell lymphoma (1 paper, 2017). "For the mouse-centric counterpart, u(MB, HB), BCL6 and GATA4 were central genes, associated with B-cell lymphoma and atrioventricular diseases respectively; GATA4 has also recently been linked to stress response and age-related inflammation in multiple tissues including the brain." (PMID 29161290, 2017).